CRP (C-reactive protein)
Diseases named in the same sentence as CRP in open-access papers (continued):
Sharing a sentence is not in itself a finding about the gene and the disease.
Sepsis (continued). "The correlation analysis results showed that in sepsis patients, the DIC score was strongly correlated with the clinical infection indicators PCT (r = 0.5542, P < 0.0001) and CRP (r = 0.5542, P < 0.0001) (r = 0.4154, P = 0.0009)." (PMID 38213768, 2024). "The results indicated that Neu (%), PCT, CRP, SAA, MPO-DNA, and cf-DNA were significant influencing factors for sepsis (p < 0.05)." (PMID 39457503, 2024). "MDW represents a reliable biomarker for sepsis screening; MDW has predictive capabilities similar to PCT and CRP." (PMID 39852198, 2024). "Compared with CRP and PCT, CRISP3 had an outperformed ability to discriminate sepsis from non-sepsis individuals." (PMID 39624089, 2024). "In our study, the CRP level and WBC, generic inflammatory markers, correlated inversely with apoB-depleted plasma’s anti-inflammatory capacity in patients with sepsis, consistent with the concept of inflammation-induced HDL dysfunction." (PMID 38603717, 2024). "Biomarkers like procalcitonin (PCT), C-reactive protein (CRP), and lactate play pivotal roles in sepsis diagnosis and monitoring." (PMID 39108794, 2024). "In multiple logistic regression, SAA, CRP, and PCT were found to be independent predictors of sepsis." (PMID 38182736, 2024). "Meanwhile, we evaluated the AUCs of CRP, PCT, and SOFA, and the results indicated that the AUCs for sepsis after trauma were 0.605 (0.463–0.735), 0.554 (0.412–0.689), and 0.754 (0.618–0.861), respectively." (PMID 39624089, 2024). "Among the biomarkers, CRP and PCT values were markedly lower in sepsis mimics than in the confirmed sepsis group." (PMID 38280062, 2024). "On the seventh postoperative day, severe left-sided abdominal pain, fever, nausea, vomiting, rising levels of C-reactive protein (CRP > 200 mg/dL), and signs of septicemia were observed." (PMID 39246919, 2024). "The neutrophil-albumin ratio (NAR), platelet-lymphocyte ratio (PLR), and C-reactive protein (CRP)-albumin ratio (CAR) are other promising biomarkers for use in patients with cancer, sepsis, and heart failure." (PMID 38222994, 2024). "C-reactive protein (CRP), synthesized in the liver, served a critical function as an inflammatory agent combating bacterial infection and sepsis." (PMID 39347502, 2024). "The specific objectives include determining which marker—IL-6, CRP, PCT or lactic acid—is most effective for predicting the prognosis of sepsis." (PMID 39589972, 2024). "In this study, we explored the accuracy of two new sepsis biomarkers, MDW and PSP, compared to traditional ones, C-reactive protein (CRP) and Procalcitonin (PCT), to predict ICU mortality by analyzing their kinetic at different time points during ICU stay." (PMID 38831992, 2024). "Traditionally, leukocytosis and high concentrations of C-reactive protein (CRP) have been related to infection and, together with clinical features, have been used to identify sepsis and drive therapeutic decision-making." (PMID 38256033, 2024). "The patient was positive for sepsis markers (TLC: 33,7000 per cubic mm with N: 61%, L: 32%, M: 6%; TPC: 346,000 per cubic mm; CRP: 136.5 mg/L, PCT: 1.2 ng/ml), had a low Hb concentration (9.1 g/dL), and had normal serum biochemical and urinalysis results." (PMID 39114240, 2024). "Similar findings have been reported in previous studies involving patients with sepsis and infected diseases, in which the nCD64 index demonstrated superior predictive efficacy compared to indicators such as PCT and CRP." (PMID 38424643, 2024). "Her complaints peaked at the top on the seventh postoperative day with severe abdominal pain, especially on the left side, fever, nausea, vomiting, and rising levels of C-reactive protein (CRP > 200 mg/dL), signs of septicemia." (PMID 39246919, 2024). "In confirming sepsis and predicting mortality, PSP outperformed CRP and PCT in terms of sensitivity." (PMID 39295616, 2024).
Sepsis (continued). "Its normal serum concentration is <5 pg/mL, and it rapidly increases after infection, with a peak within 2 h that often precedes the fever and the rise in CRP and PCT, and reaches values > 500 pg/mL in sepsis." (PMID 38256033, 2024). "Conversely, the sepsis group had greater levels of CRP, PCT, HbA1c, and WBC in comparison to the non-sepsis group." (PMID 38771840, 2024). "Studies have demonstrated that inflammatory markers such as CRP, PCT, and IL-6 are commonly utilized indicators to reflect the degree of inflammatory response in sepsis and predict disease severity." (PMID 38947447, 2024). "For example, a recent study identified elevated PSP and CRP levels in patients with sepsis, with PSP predicting pediatric sepsis with 80% sensitivity and AUC values for CRP and PSP of 0.917 and 0.868, respectively." (PMID 39295616, 2024). "Biomarkers have emerged as valuable tools for identifying and predicting sepsis outcomes, with pancreatic stone protein (PSP), procalcitonin (PCT) and C-reactive protein (CRP) as three promising candidates." (PMID 39416748, 2024). "In a multicenter cross-sectional study, patients with sepsis showed a significant increase in HBP levels, which were positively correlated with PCT, CRP, counts of neutrophils and monocytes, creatinine, bilirubin, and lactate." (PMID 39193501, 2024). "In this regard, various researchers mentioned CRP, WBC count, and PCT tests as significant biomarkers for diagnosing sepsis and initiating prompt antibiotic therapy." (PMID 38247605, 2024). "By qRT-PCR, the azurophilic granule genes CD63 and PLAC8 showed higher sepsis than SIRS levels in LD granulocytes and PLAC8 also in total granulocytes where its discriminatory performance resembled C-reactive protein (CRP)." (PMID 39434093, 2024). "Results highlight the role of C-reactive protein and APACHE II score in both populations, whereas mean platelet volume and eosinophil counts show higher importance in sepsis patients and SOFA score and platelet count show higher importance for SIRS patients." (PMID 38489347, 2024). "A risk score that includes both blood tests, glucose changes, and CRP levels for early LOS diagnosis in NICU preterm and term neonates is the Sepsis Prediction Score (SPS) presented in 2023." (PMID 39858292, 2024). "The role of conventional inflammatory biomarkers (CRP and PCT) in the diagnosis of sepsis/septic shock and the prediction of prognosis is controversial." (PMID 38708489, 2024). "Concerning female sex, ICU stays, inotrope administrations, sepsis comorbidity, and WBC—neutrophil—CRP counts, values were statistically lower for the survivors versus those of the deceased." (PMID 38534700, 2024). "As a result of the judicious selection of electrode design, it is possible to detect sepsis biomarkers with unprecedented sensitivity, reaching LODs of 0.82 ag mL−1 for PCT, 0.167 ng mL−1 for CRP, 0.202 pg mL−1 for TNF-α, and 0.056 fg mL−1 for IL-6." (PMID 38920613, 2024). "Despite the growing number of potential sepsis biomarkers that were identified, PCT and CRP were the most frequently explored." (PMID 39624089, 2024). "A previous study reported that levels of sTREM-1 in urine are more sensitive than levels of leukocytes, CRP, and PCT for the early diagnosis of sepsis and for dynamically evaluating its severity and prognosis." (PMID 38611690, 2024). "High-dose vitamin C infusion was more effective than high-dose thiamine infusion in sepsis as it reduced the SOFA score, CRP level, duration of vasopressor therapy as well as serious adverse events." (PMID 39776708, 2024). "High values of dichotomised CRP, PCT, WBC and temperature (positive test) were tested against confirmed sepsis (positive outcome) among presumed sepsis patients." (PMID 38280062, 2024). "We observed significantly elevated serum levels of PSP, CRP, and PCT in patients with confirmed sepsis compared to those with suspected sepsis." (PMID 39295616, 2024).
Sepsis (continued). "In recent years, there has been considerable interest in utilising the C-reactive protein (CRP)/albumin ratio (CAR) to evaluate the condition and forecast the prognosis of patients with sepsis." (PMID 38938850, 2024). "CRP, PCT, WBC and temperature were found to have low to moderate discriminatory power in distinguishing confirmed sepsis from sepsis mimics." (PMID 38280062, 2024). "On the other hand, CRP and PCT were inferior to interleukin-6 (IL-6) predicting treatment success in 328 patients with sepsis when re-assessed after 48–72 h." (PMID 37204560, 2024). "The elevated mean CRP (102.3 mg/L) and PCT (5.4 ng/mL) levels in this cohort are in line with previous reports that have highlighted the role of these biomarkers in sepsis." (PMID 39469363, 2024). "Our findings indicate that extended CBC parameters, such as NLR and MDW values, in addition to increased conventional CRP and PCT markers, can be utilized to predict postoperative sepsis in patients undergoing cardiovascular surgery." (PMID 39336599, 2024). "C-reactive protein (CRP) and procalcitonin (PCT) are widely recognized biomarkers used in the diagnosis and management of sepsis." (PMID 39184737, 2024). "On analyzing our cohort population, the importance of CRP, PCT, and IL-10 in diagnosing and managing sepsis is more evident." (PMID 39507174, 2024). "DEX administration reduces C-reactive protein (CRP) and procalcitonin levels in patients with sepsis requiring mechanical ventilation, improves albumin levels, and alleviates inflammation." (PMID 39881865, 2024). "As an example, the biomarker panel of procalcitonin (PCT), C-reactive protein (CRP), and serum amyloid A (SAA) seems to be predictive of sepsis." (PMID 38279209, 2024). "A retrospective study found that when patients had high levels of CRP, PCT, and IL-6, their sepsis mortality rate was relatively higher." (PMID 38947447, 2024). "Our study reinforces the critical role of inflammatory biomarkers in the early detection and prediction of sepsis in ICU patients, identifying CRP and MDW as the most sensitive and specific indicators, with MDW demonstrating a high predictive capacity." (PMID 39776743, 2024). "NeuX, NeuY, NeuZ, MonX, MonZ and RDW proved to be useful parameters for early diagnosis of sepsis and performed better than using PCT and/or CRP alone." (PMID 38337856, 2024). "Out of the several biomarkers that have been examined, C-reactive protein (CRP) and procalcitonin (PCT) have shown great potential as candidates for sepsis due to their connection with the inflammatory and infectious processes that cause it." (PMID 39469363, 2024). "C-reactive protein (CRP) and serum albumin have been shown to have utility in predicting outcomes in patients with sepsis including those with BSI." (PMID 39252713, 2024). "IL-6 exhibits a quicker response to infections than CRP and PCT, establishing its reputation as a prominent early biomarker for sepsis, notably in China." (PMID 39201697, 2024). "The area under the diagnosis curve of the nCD64 index, evaluated as the difference between the sepsis and locally infected group, was 0.777, which was higher than for PCT (0.735) and hs-CRP (0.670)." (PMID 39201697, 2024). "The hazard ratios of 1.25 for SOFA score, 1.5 for CRP, and 1.68 for PCT reinforce findings from previous studies that have identified these variables as independent predictors of mortality in sepsis." (PMID 39469363, 2024). "In this study, we first compared the accuracy of two new promising sepsis biomarkers, i.e., MDW and PSP, in relation to the traditional ones, i.e., CRP and PCT." (PMID 38831992, 2024). "The utility of CRP and PCT as biomarkers in sepsis has been the subject of numerous studies, which have generally supported their roles in early diagnosis and risk stratification." (PMID 39469363, 2024). "PSP, CRP, and PCT were statistically significant in confirming sepsis (p = 0.002, 0.01, and 0.03, respectively)." (PMID 39295616, 2024).
Sepsis (continued). "The potential of CRP, PCT, and leukocyte count changes, either individually or in combination, to predict prognosis in patients with sepsis and septic shock remains a subject of interest." (PMID 39459346, 2024). "The determination of CRP and procalcitonin (PCT) is higher in the sepsis group compared with patients with ACLF; the serum concentrations of IL-6 and IL-10 are higher in severe sepsis and different from those in subjects with ACLF or with stable cirrhosis." (PMID 39337069, 2024). "This prospective study illustrates the high value of bioscore combining PCT, CRP and SAA, which shows a significant predictive value for sepsis in severe post-traumatic patients." (PMID 38182736, 2024). "In recent years, an increasing number of biomarkers, including CRP, PCT, and IL-1β, are being utilized in clinical settings to enhance, have been explored for their potential to improve the predictive accuracy of sepsis prognosis." (PMID 39850096, 2024). "Deceased patients with sepsis secondary to BSI have significantly elevated levels of CRP, lower serum albumin concentrations, and significantly higher mean CRP/albumin ratio." (PMID 39252713, 2024). "Our study demonstrated a significant correlation between sTREM-1 levels and other commonly used sepsis biomarkers, including IL-6, lactate, PCT, and CRP." (PMID 39655134, 2024). "nCD64 has been shown in numerous studies to have good sensitivity and specificity for detecting sepsis when compared to other global indicators of inflammation as PCT and CRP." (PMID 39429998, 2024). "This study demonstrates that both CRP and PCT are valuable biomarkers for the early diagnosis and prognosis of sepsis in ICU patients." (PMID 39469363, 2024). "The ability of CRP, PCT, WBC and body temperature to discriminate between sepsis mimics and confirmed sepsis was tested using ROC analysis." (PMID 38280062, 2024). "Meta-analyses and studies have demonstrated that the pooled sensitivity and specificity of PSP for diagnosing sepsis range from 0.77 to 0.86 and 0.73 to 0.78, respectively, comparable to PCT and CRP." (PMID 39201697, 2024). "A prospective observational study of patients undergoing sepsis code activation was conducted to identify appropriate combinations of biomarkers (MR-proADM, PCT, CRP, and lactate) or clinical scores (SOFA and APACHE II) to address this clinical need." (PMID 38891025, 2024). "Clinical severity scores (i.e., APACHE II and SOFA scores) and clinical parameters such as CRP, PCT, and blood lactate levels were measured to reflect sepsis severity." (PMID 39359725, 2024). "Concentrations of sepsis biomarkers (presepsin, PCT, and CRP) were evaluated on admission and during the course of the disease." (PMID 37313382, 2023). "For instance, both C-reactive protein (CRP) and erythrocyte sedimentation rate (ESR) represent inflammation in pediatric sepsis pathology, thus they would be highly correlated." (PMID 36793336, 2023). "miR‐126‐5p expression was negatively correlated with IL‐6, CRP, and PCT but positively correlated with IgA, IgM, and IgG as well as CD3+, CD4+, and CD8+ in patients with sepsis‐induced ALI." (PMID 37248197, 2023). "Similar to patients with other severe inflammatory conditions, such as sepsis, most of the COVID–19 patients in this study were admitted to the ICU with high levels of CRP, lymphopenia, an elevated neutrophil count, and high NLR." (PMID 37600829, 2023). "CRP increase can be triggered by various events and stimuli, such as trauma, systemic inflammatory response syndrome (SIRS), sepsis, cardiovascular, and rheumatological diseases." (PMID 36769613, 2023). "The aim of the study was to assess the accuracy of PSP, compared to C-Reactive Protein (CRP), and Procalcitonin (PCT) for sepsis diagnosis in pediatric patients." (PMID 37805604, 2023).
Sepsis (continued). "Compared with neonates in the pneumonia group, neonates in the sepsis group were older, had a higher body temperature, respiratory rate, and heart rate, and had higher levels of PCT, CRP, ALT, and neutrophil count, and lower levels of ALB and SaO2/FiO2." (PMID 36908271, 2023). "IL-6 is a key factor in the regulation of acute-phase proteins, such as CRP, and was positively correlated with CRP and sCD137 in our SIRS/sepsis cohort." (PMID 38139346, 2023). "The sensitivity of CRP for the diagnosis of culture-proven EOS increased from 35% to 79% and 89% when serial blood samples were drawn at the initial sepsis workup, after 8–24 h, and after 8–48 h." (PMID 37627653, 2023). "The comparison between CRP and procalcitonin (PCT) in sepsis recognition and management of antimicrobial therapy is frequently made, however, none of them was consensually recognized as an ideal biomarker for sepsis." (PMID 37138222, 2023). "The highest levels were recorded in patients with severe sepsis or septic shock requiring RRT, with better profiles than other classical biomarkers such as CRP or PCT." (PMID 37629236, 2023). "Studies comparing nCD64 with C reactive protein (CRP), procalcitonin (PCT), and other common biomarkers of sepsis including white blood cell (WBC) count and interleukin-6 (IL-6) have found a superior performance of nCD64 in early detecting sepsis." (PMID 37746077, 2023). "In a prospective study of 80 children with suspected sepsis in the pediatric intensive care unit (PICU), PCT levels were superior to CRP levels or WBC counts in diagnosing severe infections." (PMID 38029254, 2023). "Consistently, a recent study showed that levels of C-reactive protein (CRP), TNF-α, and IL-6 decreased significantly after CRRT in patients with sepsis-induced acute kidney injury (AKI)." (PMID 36650427, 2023). "Serum IL-6 starts highly elevated in cases of culture-confirmed sepsis on DOL 1, whereas CRP takes 48 h to reach its peak." (PMID 36216867, 2023). "The peripheral blood of patients with sepsis‐induced ALI was obtained, and the levels of inflammatory factors (interleukin‐6 [IL‐6], C‐reactive protein [CRP], and procalcitonin [PCT]) were determined." (PMID 37248197, 2023). "In severe inflammatory states like sepsis where 30% increases in RMR have been observed, CRP concentrations can increase by 100,000%, whereas we observed a median 112% increase in CRP two days after influenza vaccination." (PMID 38100425, 2023). "We collected clinical data and looked at inflammatory markers such as CRP and IL-6 and cardiac markers such as troponin T. We also reported the incidence of ARDS, sepsis, and death of each patient, and compared the 2 groups." (PMID 37662725, 2023). "Several molecules, including lactic acid, c-reactive protein (CRP), procalcitonin (PCT), and B-type natriuretic peptide (BNP), have been proposed as candidate sepsis biomarkers." (PMID 37946144, 2023). "The primary outcomes extracted from the finalized research papers were the role of CRP and PCT levels, development of systemic inflammatory response syndrome (SIRS), sepsis, or death." (PMID 37868476, 2023). "Although several studies have reported the usefulness of P-SEP as a prognostic biomarker for sepsis, similar to the present study, it is difficult to predict the prognosis of sepsis based on PCT and CRP levels." (PMID 36989333, 2023). "Third, owing to the lack of data, we were unable to obtain specific sites of infection as well as objective laboratory indicators of the severity of the inflammatory response to sepsis, such as lactate, PCT, and C-reactive protein levels." (PMID 37964887, 2023). "Currently, markers of sepsis such as white blood cell count (WBC) and C-Reactive Protein (CRP) are commonly used in critical care illness despite their non-specificity for sepsis." (PMID 37238265, 2023).